RICTOR (RPTOR independent companion of MTOR complex 2)
Diseases named in the same sentence as RICTOR in open-access papers (continued):
Sharing a sentence is not in itself a finding about the gene and the disease.
diabetic kidney disease (2 papers, 2022 to 2025). Progressive kidney disorder caused by vascular damage to the glomerular capillaries, in patients with diabetes mellitus. "MiRNA-424 facilitates diabetic nephropathy progression through targeting RICTOR both in diabetic nephropathy rat models and high-glucose–induced glomerular mesangial cell models." (PMID 35620059, 2022). "Consistently, a previous study has detected the significant overexpression of RICTOR in renal tissues of diabetic nephropathy rat models." (PMID 35620059, 2022). "Although the expression of EIF4B, RICTOR, and PRKCB was verified in a diabetic nephropathy rat model, a deeper analysis should be conducted for confirming their functions in diabetic nephropathy progression." (PMID 35620059, 2022). "The expression of mTOR pathway markers EIF4B, RICTOR, and PRKCB was verified in kidney tissues from the control group and the diabetic nephropathy rat model group." (PMID 35620059, 2022). "To verify the expression of EIF4B, RICTOR, and PRKCB proteins, we established a diabetic nephropathy rat model." (PMID 35620059, 2022). "Our data showed that in comparison to the control group, EIF4B, RICTOR, and PRKCB displayed markedly higher mRNA expression in diabetic nephropathy rats." (PMID 35620059, 2022). "Differentially expressed marker genes of immune cells EIF4B, RICTOR, and PRKCB were significantly enriched in the mTOR pathway, which were confirmed to be up-regulated in diabetic nephropathy." (PMID 35620059, 2022). "Meanwhile, Western blot results confirmed the significant up-regulation of EIF4B, RICTOR, and PRKCB proteins in kidney tissues of diabetic nephropathy rats than that of control rats." (PMID 35620059, 2022). "The GSE111154 and GSE142025 datasets were utilized for validating the expression of mTOR pathway markers EIF4B, RICTOR, and PRKCB in the kidneys from controls and diabetic nephropathy patients." (PMID 35620059, 2022). "Also, we established diabetic nephropathy rat models; marker genes (EIF4B, RICTOR, and PRKCB) of the immune cells were confirmed to be up-regulated in diabetic nephropathy." (PMID 35620059, 2022). "Collectively, marker genes of immune cells EIF4B, RICTOR, and PRKCB in the mTOR pathway might participate in diabetic nephropathy progression." (PMID 35620059, 2022).
heart failure (2 papers, 2022 to 2024). Inability of the heart to pump blood at an adequate rate to meet tissue metabolic requirements. "Specifically, our results highlight distinct genomic regions implicated in the predisposition to cardiomyopathy and heart failure for GFM1, and heart failure and aortic aneurysm for RICTOR, diseases that negatively affect survival in humans." (PMID 38293129, 2024). "RICTOR also leads to activation of Paxillin (PXN), a focal adhesion protein whose inactivation results in a progressive decrease of cardiac contractility and heart failure." (PMID 35310970, 2022).
liver cancer (2 papers, 2020 to 2021). An epithelial or non-epithelial malignant neoplasm that arises from the liver. "We found that the RICTOR gene was genetically altered in approximately 1~4% of human liver cancer cases, including mutation, fusion or amplification (Figure." (PMID 33061800, 2020). "In liver cancer, alteration frequency of the RICTOR gene accounts for approximately 4% of patient cases, including amplification, shows that the RICTOR gene may be amplified or overexpressed in HCC tissues." (PMID 33061800, 2020). "To further examine the expression levels of HMGB1 and RICTOR in the experimental context, we utilized the DEN + CCl4-induced liver cancer model in C57 mice." (PMID 34916485, 2021).
liver fibrosis (2 papers, 2020 to 2022). "To examine the role of other targets in the therapeutic effect of miR-451/miR-185 agomirs, we detected the protein expression of three representative liver fibrogenesis-related target genes including c-myc, RHEB and RICTOR in CCl4-induced liver fibrosis mice." (PMID 32467578, 2020).
medulloblastoma (2 papers, 2016 to 2021). A malignant, invasive embryonal neoplasm arising from the cerebellum.
metastatic melanoma (2 papers, 2021 to 2024). A melanoma that has spread from its primary site to another anatomic site. "Thus, low expression of RICTOR in metastatic melanoma is associated with a poor clinical outcome, and the gene expression signature of low RICTOR tumors indicates the activation of processes that are frequently associated with BRAF/MEKi resistance." (PMID 38755661, 2024). "Importantly, our findings indicate that the evaluation of intra-tumor RICTOR levels has a prognostic value in metastatic melanoma and may help to guide therapeutic strategies in a personalized manner." (PMID 38755661, 2024).
osteoporosis (2 papers, 2019 to 2021). A condition of reduced bone mass, with decreased cortical thickness and a decrease in the number and size of the trabeculae of cancellous bone (but normal chemical composition), resulting in increased fracture incidence. "Materials and methods: The expression of miR-152 and RICTOR were tested in ovariectomized rat models of osteoporosis." (PMID 31492082, 2019). "Interestingly, the repression of miR-152 promoted osteoblast differentiation and mitigated osteoporosis through the upregulation of RICTOR." (PMID 35011442, 2021). "An increased miR-152 and decreased RICTOR were found in osteoporosis." (PMID 31492082, 2019). "Hence, these findings suggested the abnormal expression of miR-152 and RICTOR in osteoporosis." (PMID 31492082, 2019). "Importantly, inhibiting miR-152 could up-regulate the expression of its target gene RICTOR to improve the viability of osteoblasts and promote osteoblast differentiation, which is expected to provide alternative strategies and research perspective for the prevention and treatment of osteoporosis." (PMID 31492082, 2019).
osteosarcoma (2 papers, 2015 to 2017). A usually aggressive malignant bone-forming mesenchymal neoplasm, predominantly affecting adolescents and young adults. "The co-amplification of TERT and RICTOR was only seen in osteosarcoma." (PMID 28643781, 2017).
pancreatic ductal adenocarcinoma (2 papers, 2017 to 2025). An infiltrating adenocarcinoma that arises from the epithelial cells of the pancreas. "However, the role of RICTOR in human pancreatic ductal adenocarcinoma (PDAC) is unclear so far." (PMID 28445935, 2017).
skin cancer (2 papers, 2017 to 2021). "Interestingly, skin cancer cell line ANST showed overall diverse behavior, regarding downregulation of Cyclin D1, Myc, and SMAD3 as well as upregulation of MARCKS and RICTOR, compared to all other tested cell lines." (PMID 34722291, 2021). "This is in contrast to results from Carr and coworkers who showed that depletion of RICTOR in established skin tumors led to tumor regression without changes in tumor cell proliferation." (PMID 28445935, 2017).
squamous cell carcinoma (2 papers, 2023 to 2024). A carcinoma arising from squamous epithelial cells. "RICTOR gene, which encodes the scaffold protein of mTORC2, can be amplified in various tumor types, including squamous cell carcinoma (SCC) of the lung." (PMID 38706776, 2024). "Additionally, we found a positive relationship between RICTOR expression and the immune infiltration of macrophages and cancer-associated fibroblasts in Colon adenocarcinoma and Head and Neck squamous cell carcinoma." (PMID 37372460, 2023).
acral melanoma (1 paper, 2020). "The driver mutations in the genes RICTOR, CDK4, PDGFRA, KIT were specific for acral melanoma, while the amplification or deletion of the genes CCND2 and CHEK2 are uniquely found in mucosal melanoma." (PMID 32825510, 2020).
bladder tumor (1 paper, 2020). "Though PKC-alpha and RICTOR are in the mTOR signaling pathway in the bladder tumor, it is uncertain that the PKC-alpha and RICTOR are the mTOR signaling pathway." (PMID 32802870, 2020). "However, there has been no publication about the correlation between the PKC-alpha, JNK2, RICTOR, and TSC-1 in bladder tumor." (PMID 32802870, 2020).
Bladder Urothelial Carcinoma (1 paper, 2023). "By analyzing the tissue origin, Bladder Urothelial Carcinoma BC3C is the most sensitive cell line, and Non-Hodgkin Lymphoma is the most sensitive disease for RICTOR knockout." (PMID 37372460, 2023).
bone metastasis (1 paper, 2021). Transfer of a neoplasm from its primary site to bones. "The associations of ESR1 mutations with liver metastasis and RICTOR mutations with bone metastasis were significant, irrespective of the intrinsic subtypes." (PMID 34272397, 2021). "In metastatic site-specific analyses, associations of ESR1 with liver metastasis and RICTOR with bone metastasis were significant, regardless of intrinsic subtypes." (PMID 34272397, 2021).
bone sarcoma (1 paper, 2023). A sarcoma that arises from the bone.
cerebrovascular disease (1 paper, 2024). "Similarly, RICTOR SNPs were associated with these diseases as well as cerebrovascular disease, vascular dementia, and Parkinson’s disease." (PMID 38293129, 2024).
cervical tumors (1 paper, 2021).
Cirrhosis (1 paper, 2024). A chronic disorder of the liver in which liver tissue becomes scarred and is partially replaced by regenerative nodules and fibrotic tissue resulting in loss of liver function. "Stem cells: Compared to controls, LXR/RXR and RICTOR signaling pathways were activated in compensated cirrhosis but inflammatory pathways (IFNG, TNF) were downregulated." (PMID 38369527, 2024).
cutaneous melanoma (1 paper, 2024). A primary melanoma arising from atypical melanocytes in the skin. "The clinical significance of our findings is supported by analysis of the cutaneous melanoma subset in the TCGA database, which reveals a positive correlation between lower RICTOR protein and poorer outcomes in patients with BRAFV600E mutations." (PMID 38755661, 2024).
esophageal adenocarcinoma (1 paper, 2019). A malignant tumor with glandular differentiation arising predominantly from Barrett mucosa in the lower third of the esophagus. "Use case – Esophageal adenocarcinoma with reported amplification ofCCND1,MAP2K1,RICTOR,FGF10,FGF19,FGF3,FGF4 andMCL1." (PMID 31608148, 2019).
esophageal squamous cell carcinoma (1 paper, 2022). Esophageal squamous cell carcinoma (ESCC) is a type of esophageal carcinoma (EC) that can affect any part of the esophagus, but is usually located in the upper or middle third. "Activation of the mTORC2 subunit p-AKT (Ser473) and RICTOR stimulate the esophageal squamous cell carcinoma." (PMID 35402264, 2022). "Inhibiting RICTOR may increase esophageal squamous cell carcinoma cell sensitivity to PP242 (a pan-mTOR inhibitor) as well as RAD001 (a mTORC1 inhibitor)." (PMID 35402264, 2022).
Hirschsprung disease (1 paper, 2023). Hirschsprung disease (HSCR) is a congenital intestinal motility disorder that is characterized by signs of intestinal obstruction due to the presence of an aganglionic segment of variable extent in the terminal part of the colon. "Taken together, our present study indicates a critical role of miR-424 and its direct target RICTOR in the risk of Hirschsprung disease." (PMID 37047673, 2023). "Of interest, we have for the first time identified decreased expression of RICTOR at both the mRNA and protein levels in the normoganglionic dilated segment of the HSCR colon, suggesting that the modulation of RICTOR may change during the progression of Hirschsprung disease." (PMID 37047673, 2023).
Hyperglycemia (1 paper, 2017). An increased concentration of glucose in the blood. "Since hyperglycemia is commonly found in PDAC, this mechanism might play an additional role in RICTOR's protumorigenic effects in PDAC." (PMID 28445935, 2017).
Hypertension (1 paper, 2019). The presence of chronic increased pressure in the systemic arterial system. "The inhibition of RICTOR and IRF7signalling persisted through this stage of hypertension development." (PMID 29651914, 2019).
intestine cancers (1 paper, 2019). "Interestingly, 6 somatic mutations in the RICTOR gene were identified in 6 S-LAM patients separately in this study and somatic RICTOR mutations related to stomach and intestine cancers were documented in the COSMIC database." (PMID 31856217, 2019).
leiomyosarcoma (1 paper, 2013). An uncommon, aggressive malignant smooth muscle neoplasm, usually occurring in post-menopausal women. "One patient had a leiomyosarcoma, where alterations of the mTOR pathway have been described, such as the overexpression of RICTOR, a major component of the mTOR complex 2, which might contribute to the pathogenesis of well-differentiated leiomyosarcoma." (PMID 24216984, 2013).
leukemia (1 paper, 2024). A malignant (clonal) hematologic disorder, involving hematopoietic stem cells and characterized by the presence of primitive or atypical myeloid or lymphoid cells in the bone marrow and the blood. "Specific inhibition of mTORC2 has therapeutic potential in AML, as genetic depletion of RICTOR in a mouse model led to overactivation of mTORC1 and exhaustion of leukemia stem cells." (PMID 39259491, 2024). "Higher doses might be required in leukemia cells to inhibit mTOR binding to RICTOR, but we did not detect any decrease in AKT pSer473 levels following treatment of Jurkat cells with up to 50 μM JR-AB2-011." (PMID 39259491, 2024).
malignant glioma (1 paper, 2023). A grade III or grade IV glioma arising from the central nervous system. "Furthermore, animal experiments have suggested that overexpression of RICTOR induced malignant glioma formation in a transgenic mouse model." (PMID 36909198, 2023).
malnutrition (1 paper, 2022). Inadequate nutrition resulting from poor diet, malabsorption, or abnormal nutrient distribution. "On the other hand, consistently reduced expressions of the RICTOR gene among the malnourished group with respect to that among the healthy control group indicate a potential role of the mTORC2 pathway with childhood malnutrition." (PMID 35458174, 2022).
meningioma (1 paper, 2016). A generally slow growing tumor attached to the dura mater.
mental disorder (1 paper, 2021). A disease that has its basis in the disruption of mental process. "Moreover, RICTOR is also associated with the pathological mechanisms of other mental disorders." (PMID 34348681, 2021).
Merkel cell carcinomas (1 paper, 2016). "Importantly, aberrations in the PI3K/AKT/mTOR pathway (AKT2, FBXW7, NF1, PIK3CA, PIK3R1, PTEN or RICTOR) were also commonly seen in Merkel cell carcinomas (9/17 [53%])." (PMID 26981779, 2016).
mesenchymal tumors (1 paper, 2022). "We also compared the protein level data and found that PI3K pathway activators like TSC1, 4EBP1 and p4EBP1, PI3K-p85, RICTOR-pT1135 were significantly increased in high mesenchymal tumors, and PI3K inhibitor like LKB1 and INPP4B expression was significantly decreased." (PMID 36120580, 2022).
microcephaly (1 paper, 2025). A congenital or acquired developmental disorder in which the circumference of the head is smaller than normal for the person's age and sex. "In cones, several genes associated with cell migration (LARGE1), mechanistic target of rapamycin (mTOR) signaling (RICTOR), microcephaly (XRCC4), and intellectual developmental disorder (FMN2) were strongly dysregulated." (PMID 40706588, 2025).
myeloma (1 paper, 2020). "Among the genes uniquely expressed following Ix-treatment in resistant myeloma were RICTOR (activated), HNF4A, miR-16-5p (activated), MYCN (inhibited), and MYC (inhibited)." (PMID 32724061, 2020).
myocardial infarction (1 paper, 2022). Gross necrosis of the myocardium, as a result of interruption of the blood supply to the area, as in coronary thrombosis. "Cells with genetic deletion of RICTOR exhibit defects in cell polarity and cytoskeletal architecture, whereas cardiac-specific knockdown of RICTOR exacerbated cardiac remodeling and dysfunction after myocardial infarction." (PMID 35310970, 2022).
nephropathies (1 paper, 2021). "Accordingly, a considerable number of studies have shown the involvement of mTOR and RICTOR in nephropathies." (PMID 34638634, 2021).
neuroblastoma (1 paper, 2023). Neuroblastoma (NB) is the most common solid, extracranial childhood tumor. "To test whether human RICTOR is regulated by miR-424, we assessed its expression in human SH-SY5Y neuroblastoma cells transfected with synthetic miR-424 mimics or inhibitors." (PMID 37047673, 2023).
neuroendocrine tumors (1 paper, 2018). "In addition, we identify amplified PIK3CA and RICTOR as potential biomarkers for patients with neuroendocrine tumors with increased propensity to respond to treatment with AKT inhibitors." (PMID 29951225, 2018). "In addition, our data suggest that PIK3CA and RICTOR gene co-amplification may define a unique subset of patients with neuroendocrine tumors that will respond to AKT inhibitors, and could thus be used as an additional biomarker for treatment stratification." (PMID 29951225, 2018).
prostate adenocarcinoma (1 paper, 2021). "In contrast, in prostate adenocarcinoma tissues, UCP2 expression is reduced, while several MAM-stabilizing proteins, including AKAP1, RICTOR, GPR75, and PEMT1, were found to be upregulated." (PMID 33614647, 2021).
renal carcinoma (1 paper, 2023). A carcinoma arising from the epithelium of the renal parenchyma or the renal pelvis. "To explore to what extent the marked effects of PHT cell CM on HepG2 cell IGFBP-1 phosphorylation is specific to trophoblast cells, we examined the impact of CM collected from renal carcinoma cells in which RAPTOR or RICTOR was silenced." (PMID 37108437, 2023).
renal fibrosis (1 paper, 2021). A final common manifestation of a wide variety of chronic kidney diseases characterized by glomerulosclerosis and tubulointerstitial fibrosis. "Recently, RICTOR has been implicated in renal fibrosis development, specifically in association with TGFB1-induced fibroblast activation and epithelial–mesenchymal transition." (PMID 34063776, 2021).
schizophrenia (1 paper, 2021). A major psychotic disorder characterized by abnormalities in the perception or expression of reality. "Experiments with RICTOR KO animals have identified an important role for this gene in the pathogenesis of schizophrenia." (PMID 34348681, 2021). "The MTOR and RICTOR mRNA expression levels in patients with acute schizophrenia were significantly decreased compared with those of healthy controls and further significantly decreased after four weeks of olanzapine treatment." (PMID 34348681, 2021). "In the present study, the RICTOR mRNA expression level was significantly lower in patients with acute schizophrenia before treatment than in healthy controls and did not change significantly after olanzapine treatment." (PMID 34348681, 2021).